ASF1B (anti-silencing function 1B histone chaperone)
Diseases named in the same sentence as ASF1B in open-access papers (continued):
Sharing a sentence is not in itself a finding about the gene and the disease.
melanoma (4 papers, 2015 to 2022). A malignant, usually aggressive tumor composed of atypical, neoplastic melanocytes. "In this study, we have attempted to obtain a thorough understanding of the mechanism of the miR-520d-3p-ASF1B axis in melanoma." (PMID 34872448, 2021). "The results suggested that ASF1B effectively elevated cellular proliferation and adhesion and hampered cellular apoptosis in melanoma cells." (PMID 34872448, 2021). "We studied the effect of the miR-520d-3p-ASF1B axis on the malignant behavior of melanoma cells in vitro and found that miR-520d-3p suppresses ASF1B to hamper the progression of melanoma based on the targeted regulatory mechanisms of miRNAs and mRNAs." (PMID 34872448, 2021). "Overexpression of ASF1B enhanced cell growth and adhesion and hampered cell apoptosis in melanoma cells." (PMID 34872448, 2021). "In this study, we have revealed the mechanism of the miR-520d-3p-ASF1B axis in melanoma, providing a valuable theoretical basis for early screening and diagnosis of melanoma." (PMID 34872448, 2021). "To assess the effect of ASF1B in melanoma, we first detected the expression of ASF1B in 38 pairs of tumor and normal tissues from patients with melanoma." (PMID 34872448, 2021). "ASF1B expression was evidently increased, whereas miR-520d-3p level was downregulated in melanoma tissues and cells." (PMID 34872448, 2021). "In this study, we have shown that ASF1B expression was increased, while miR-520d-3p expression was reduced in melanoma tissues and cells." (PMID 34872448, 2021). "ASF1B expression in the melanoma tissues was obviously 4-fold higher than that in normal tissues (1.00 ± 0.44 in normal tissues, 4.32 ± 1.59 in tumor tissues)." (PMID 34872448, 2021). "The expression of anti-silencing function 1B histone chaperone (ASF1B) and miR-520d-3p in melanoma tissues and cells was detected by reverse transcription-quantitative polymerase chain reaction." (PMID 34872448, 2021). "We found an obvious increase in ASF1B expression in melanoma tissues and cells and induced ASF1B knockdown and overexpression in melanoma cells." (PMID 34872448, 2021). "ASF1B was upregulated in melanoma cells and facilitated proliferation and adhesion, but repressed cell apoptosis of melanoma cells." (PMID 34872448, 2021). "In addition, ASF1B overexpression promotes melanoma cell growth and adhesion and inhibits apoptosis." (PMID 35280822, 2022). "Moreover, the biological role of miR-520d-3p-ASF1B axis in melanoma needs to be verified and determined using animal models." (PMID 34872448, 2021). "Furthermore, although we have confirmed the interaction between miR-520d-3p and ASF1B in melanoma cells in our study, the signaling pathways involved need to be elucidated." (PMID 34872448, 2021). "In conclusion, through our study, we clarified for the first time that miR-520d-3p hampered the development of melanoma by inhibiting ASF1B expression, which could be a promising target for the clinical treatment of melanoma." (PMID 34872448, 2021). "Similarly, the melanoma cells also had significantly increased ASF1B protein levels compared to normal HaCAT cells (1.00 ± 0.08 in HaCAT, 2.68 ± 0.26 in A375, 2.92 ± 0.32 in A875, 1.92 ± 0.13 in WM35, and 0.89 ± 0.06 in A2058)." (PMID 34872448, 2021). "In conclusion, we have found out that miR-520d-3p suppressed melanoma tumorigenesis by inhibiting ASF1B, which could be a promising target for melanoma therapy." (PMID 34872448, 2021). "In addition, to investigate the role of ASF1B in melanoma, we examined the effects of ASF1B knockdown on the proliferation, apoptosis, and adhesion of melanoma cells." (PMID 34872448, 2021). "Our study may deepen our understanding of the miR-520d-3p-ASF1B axis in melanoma development and highlights the potential of the miR-520d-3p-ASF1B axis as a new target for melanoma therapy." (PMID 34872448, 2021). "miR-520d-3p hampered melanoma cell progression by inhibiting ASF1B." (PMID 34872448, 2021).
melanoma (continued). "Moreover, we verified the targeted binding between ASF1B and miR-520d-3p, and further explored the role of ASF1B in the survival of melanoma cells mediated by miR-520d-3p." (PMID 34872448, 2021). "Furthermore, ASF1B expression was negatively correlated with miR-520d-3p expression in melanoma tissues." (PMID 34872448, 2021). "Additionally, we will study the correlation between the miR-520d-3p-ASF1B axis and the prognosis of patients with melanoma and cancer histopathology once the opportunity arises." (PMID 34872448, 2021). "In our study, we have clarified that miR-520d-3p hampered the development of melanoma by inhibiting ASF1B expression, which could be a promising target for the clinical treatment of melanoma." (PMID 34872448, 2021). "In this study, we hypothesized that ASF1B is tumorigenic in melanoma and is targeted by miR-520d-3p." (PMID 34872448, 2021). "We analyzed ASF1B levels in melanoma tissues and cell lines." (PMID 34872448, 2021). "In the current study, we elucidated the role of ASF1B in melanoma progression." (PMID 34872448, 2021). "Additionally, future studies on melanoma screening and diagnosis may be carried out based on the regulatory mechanism of the miR-520d-3p-ASF1B axis." (PMID 34872448, 2021). "Therefore, to further identify the candidate miRNAs regulating ASF1B, we intersected the miRNAs predicted by TargetScan algorithm (version: 7.2) and the differentially expressed miRNAs in melanoma from GSE61741 with the criteria of adjusted P < 0.05, and logFC ≤ −1.5." (PMID 34872448, 2021). "Moreover, miR-520d-3p suppressed the progression of melanoma cells by inhibiting ASF1B expression." (PMID 34872448, 2021). "Moreover, miR-520d-3p suppressed the expression of ASF1B to suppress melanoma tumorigenesis." (PMID 34872448, 2021). "In addition to immune‐related pathways, our results suggested that ASF1B also regulates many other pathways, such as those involved in cytosolic DNA sensing, starch and sucrose metabolism, melanoma, phagocytosis, and central nervous system neuron differentiation." (PMID 34472711, 2021). "Furthermore we examined whether the miR-520d-3p-ASF1B axis plays a role in melanoma." (PMID 34872448, 2021). "In addition, ASF1B has been suggested to be a significant promoter of tumor in other cancers but has not been studied in melanoma." (PMID 34872448, 2021). "However, the role of ASF1B in melanoma has not been clearly elucidated." (PMID 34872448, 2021).
pancreatic adenocarcinoma (4 papers, 2021 to 2023). "Elevated ASF1B expression was linked to poorer OS in ACC, KIRC, KIRP, LGG, LIHC, LUAD, Mesothelioma (MESO), and Pancreatic adenocarcinoma (PAAD), whereas it was associated with better OS in Cervical squamous cell carcinoma and endocervical adenocarcinoma (CESC), STAD, and Thymoma (THYM) patients." (PMID 34568067, 2021). "Here, we employed WGCNA to identify novel hub genes including PKMYT1, WDHD1, ASF1B, and RAD18, and proposed for the first time their oncogenic roles during pancreatic adenocarcinoma progression." (PMID 35047023, 2021).
pancreatic cancer (4 papers, 2021 to 2024). "In a pancreatic cancer study, ASF1B knockdown can also suppress the tumor progression and improved the efficacy of cisplatin in the treatment of pancreatic cancer." (PMID 36114946, 2023). "In this study, we demonstrated that ASF1B is highly expressed in pancreatic cancer and its high expression promotes the migration, invasion and EMT in PDAC cells." (PMID 36114946, 2023).
acute myeloid leukemia (3 papers, 2021 to 2024). Acute myeloid leukemia (AML) is a group of neoplasms arising from precursor cells committed to the myeloid cell-line differentiation. "We began by querying the GTEx and TCGA databases, revealing pronounced ASF1B upregulation in all cancers other than Acute Myeloid Leukemia (LAML), as further confirmed using Oncomine data." (PMID 34568067, 2021).
Breast Tumors (2 papers, 2011 to 2025). "Finally, the results presented here reveal the process of RC-chromatin assembly as a potential target against cell proliferation in cancer therapy, as also suggested by a recent observation showing that human Asf1b is overexpressed in breast tumours." (PMID 22102830, 2011).
colorectal cancer (2 papers, 2021 to 2025). A primary or metastatic malignant neoplasm that affects the colon or rectum. "A study has also reported that ASF1B is positively correlated with the TNM stage of colorectal cancer patients." (PMID 40770782, 2025). "The protein expression of most hub genes and/or phosphorylation level was significantly upregulated in colorectal cancer, while the phosphorylation level of ASF1B showed no significance difference between the normal and tumor samples." (PMID 40770782, 2025).
diffuse large B-cell lymphoma (2 papers, 2021 to 2023). "For example, ASF1A is deleted in 10% of diffuse large B-cell lymphoma TCGA samples, making ASF1B a possible target." (PMID 36707513, 2023). "ASF1B expression was significantly elevated in some cancers with only a few available normal samples, such as diffuse large B‐cell lymphoma (DLBC) and ovarian cancer (OV)." (PMID 34472711, 2021).
Gastric tumor (2 papers, 2021 to 2022). "Similarly, high ASF1b expression states was observed in the Oncomine Cho Gastric and DErrico Gastric tumor samples (P<0.001)." (PMID 35399734, 2022).
ovarian carcinoma (2 papers, 2021 to 2024). A malignant neoplasm originating from the surface ovarian epithelium. "Furthermore, we confirmed that protein levels of ASF1B, CCNE1, CDC20, and RNASEH2A were significantly increased in ovarian cancer cells compared with non-transformed ovarian cells." (PMID 39199556, 2024).
Skin Cutaneous Melanoma (2 papers, 2021). "In contrast, lower expression of ASF1B was observed in several other cancers, including skin cutaneous melanoma (SKCM)." (PMID 34472711, 2021).
autoimmune thyroid disease (1 paper, 2021). Inflammatory disease of the thyroid gland due to autoimmune responses leading to lymphocytic infiltration of the gland. "ASF1B may potentially affect several key immune‐related pathways, such as those involved in antigen processing and presentation, natural killer cell‐mediated cytotoxicity, and autoimmune thyroid disease." (PMID 34472711, 2021).
cervical tumors (1 paper, 2020). "Disrupting ASF1B can prominently suppress cervical tumor growth by regulating cell cycle and apoptosis pathways." (PMID 32848135, 2020). "In the present study, we first evaluated ASF1B mRNA levels in cervical cancer tumor and para-carcinoma tissues and found that aberrantly high expression of ASF1B occurs in cervical tumors, which was confirmed by qPCR and immunohistochemical analysis." (PMID 32848135, 2020).
erythrocyte disorder (1 paper, 2026). A disease or disorder that involves the erythrocyte. "In summary, ASF1B plays a crucial role in enrichment of H3.3 nucleosomes and establishment of the chromatin environment to affect erythroid gene expression, highlighting the therapeutic potential of ASF1B in targeting erythrocyte disorders, such as β-globin hemoglobinopathies." (PMID 42100853, 2026).
Infertility (1 paper, 2019). "These genes play important roles in cell proliferation (RFX4, FOXM1, ASF1B), differentiation during spermatogenesis (CATSPERG, SPDYA, SPATA16, TSACC, TCP10L, DPY19L2) and motility of sperm cells during fertilization (DNAAF1); mutations in these genes may lead to infertility." (PMID 31671693, 2019).
malignant mesothelioma (1 paper, 2021). A malignant neoplasm of the pleura or peritoneum, arising from mesothelial cells. "Some studies have reported that ASF1B may induce differentiation of sarcomatoid phenotype as a prognostic indicator by regulating the microenvironment and epithelial-mesenchymal transition in malignant mesothelioma." (PMID 34490109, 2021).
metastatic melanoma (1 paper, 2023). A melanoma that has spread from its primary site to another anatomic site. "Among the top 5 candidate genes (UBE2C, ASF1B, FOXM1, HJURP, and KIF18B), UBE2C was the most frequently associated with poor prognosis in publicly available clinical datasets from diverse cancer types, including metastatic melanoma." (PMID 37215954, 2023).
ovarian tumors (1 paper, 2024). "Except for ATAD2, expression of other genes (ASF1B, CCNE1, CDC20, CDCA8, RECQL4, RNASEH2A, and SMC4) was upregulated in ovarian tumors compared to non-cancerous tissue." (PMID 39199556, 2024).
pancreatic ductal adenocarcinoma (1 paper, 2023). An infiltrating adenocarcinoma that arises from the epithelial cells of the pancreas. "The present work explored the functional role and the expression regulation of ASF1B in pancreatic ductal adenocarcinoma (PDAC)." (PMID 36114946, 2023).
triple-negative breast carcinoma (1 paper, 2023). An invasive breast carcinoma which is negative for expression of estrogen receptor (ER), progesterone receptor (PR), and human epidermal growth factor receptor 2 (HER2). "Other study uncovered that ASF1B activated PI3K/AKT/mTOR signaling to promote cisplatin resistance in triple-negative breast cancer cells." (PMID 37693891, 2023).
cancer (36 papers, 2011 to 2025). A tumor composed of atypical neoplastic, often pleomorphic cells that invade other tissues. "Given the significant impact of immunotherapy as an emerging treatment in improving the prognosis of cancer patients, we subsequently also investigated the potential association of ASF1B with immunotherapy." (PMID 38164276, 2024). "Here, we performed a systematic analysis of ASF1B using multiple databases, explored the expression of ASF1B in different cancers and its association with prognosis, and highlighted the importance of ASF1B in LUAD." (PMID 38164276, 2024). "For example, ASF1B overexpression was associated with worse prognosis in some cancers, including Adrenocortical carcinoma (ACC), KIRP, KIRC, and LUAD." (PMID 38164276, 2024). "A previous study showed that ASF1B is overexpressed in multiple cancers and is closely associated with cancer survival." (PMID 36947060, 2023). "The ESTIMATE algorithm was used to assess stromal and immune scores for 33 cancers and to analyze their association with ASF1B expression." (PMID 34472711, 2021). "The results showed that ASF1B expression was associated with TMB in several cancers (n = 22, p < 0.05)." (PMID 34472711, 2021). "Kaplan-Meier survival curves suggested that elevated ASF1B expression was associated with better or worse survival in a cancer type-dependent manner." (PMID 34568067, 2021). "Next, we analyzed GO functional annotations and KEGG pathways associated with ASF1B in various cancers." (PMID 34472711, 2021). "ASF1B was associated with M2 macrophages in 7 cancers, resting Mast cells and activated NK cells in 6 cancers, M0 and M1 macrophages in 7 cancers, T follicular helper cells in 11 cancers, and resting memory CD4+ T cells in 10 cancers." (PMID 34568067, 2021). "Kaplan–Meier survival analyses revealed that high ASF1B expression is associated with poor prognosis in several cancers." (PMID 34472711, 2021). "In enrichment analyses, we found ASF1B was primarily associated with immune-, proliferation-, and autophagy-related pathways, some of which were enriched in both normal tissues and cancers although the associated genes differed." (PMID 34568067, 2021). "Herein, we explored the expression and prognostic relevance of ASF1B across cancers, in addition to evaluating the association between ASF1B expression levels and molecular pathways, immune infiltration, methylation, Copy number variations (CNV), MSI, and TMB." (PMID 34568067, 2021). "Our results further clarify the broad oncologic applicability of ASF1B and confirmed that, in other cancers, the expression of ASF1B is closely associated with the biological activation of various immune cells and immune‐related cytokines." (PMID 34472711, 2021). "In addition, high expression of ASF1B level was also found to be associated with poor prognosis in different cancers." (PMID 36114946, 2023). "Therefore, ASF1B is gaining attention as a new diagnostic and prognostic biomarker as well as a therapeutic target for these cancers." (PMID 35360875, 2022). "Recent research also noted that ASF1b may serve as a prognostic biomarker associated with immunotherapy for several cancers." (PMID 35399734, 2022). "Our first pan‐cancer analysis of ASF1B results showed that this gene was highly expressed in 22 tumor tissues compared to normal tissues and revealed an association between ASF1B expression and clinical prognosis." (PMID 34472711, 2021). "Therefore, it is important to reveal the pan‐cancer associations between ASF1B expression and the TME." (PMID 34472711, 2021). "Overall, ASF1B is gaining attention as an important player in the development of several tumors and is expected to become a new diagnostic and prognostic biomarker as well as a therapeutic target for these cancers." (PMID 34472711, 2021). "In addition, ASF1B expression has been associated with cancer-related pathways." (PMID 35280822, 2022). "Moreover, we found that ASF1B expression is associated with age in some cancers." (PMID 34472711, 2021).